DRD2 (dopamine receptor D2)
Diseases named in the same sentence as DRD2 in open-access papers (continued):
Sharing a sentence is not in itself a finding about the gene and the disease.
Stroke (8 papers, 2018 to 2025). Sudden impairment of blood flow to a part of the brain due to occlusion or rupture of an artery to the brain. "DRD2, a dopamine receptor gene, is expressed in the microglia and macrophages in the brains of stroke mice and may help regulate the neuroinflammation caused by stroke." (PMID 40137146, 2025). "Therefore, SRC, EGFR, ESR1, PTGS2, and DRD2 are closely related to the occurrence and development of stroke, and the volatile compounds of musk may treat nerve damage caused by stroke by binding to these key target proteins." (PMID 40137146, 2025). "Through network pharmacology and computational simulations, key targets associated with musk volatile compounds and stroke, including SRC, EGFR, ESR1, PTGS2, and DRD2, were identified." (PMID 40137146, 2025). "Similar to Pde10a, Adora2a and Drd2 belong to the cAMP signaling pathway, which is known to regulate synaptic plasticity and be involved in functional recovery after stroke." (PMID 36833381, 2023). "In addition, network pharmacological analyses identified 180 potential targets of the major volatile compounds of musk associated with stroke, and five key targets (SRC, EGFR, ESR1, PTGS2, and DRD2)." (PMID 40137146, 2025). "Studies have demonstrated the potential of dopamine receptor D2 activators in alleviating oxidative damage following stroke, thereby identifying dopamine receptors as viable treatment targets for stroke." (PMID 37719118, 2023). "Furthermore, genes that were regulated differently following stroke in an age-dependent manner showed greater down- (or up-) regulation of gene response to stroke, including genes related to dopaminergic function (Drd1 and Drd2), in younger animals." (PMID 30034335, 2018). "However, DRD2 and C5aR1 are absent or negligible in marmoset reactive astrocytes with only ESR1 & IL6ST significantly upregulated 1-week after stroke." (PMID 34824275, 2021).
cannabis dependence (7 papers, 2012 to 2024). Physical and psychological dependence on the drug cannabis. "Other studies indicate the simultaneous presence of factors predisposing to other dependence such as inter alia heroin or cannabis dependence, including DRD2 polymorphism (rs 1800497, homzygotes) and personality traits like neuroticism, extraversion ans/or introversion, psychoticism)." (PMID 34945190, 2021). "The sensitivity of striatal PENK and DRD2 expression to delta-tetrahydrocannabinol (THC) raises the question as to whether genetic polymorphisms of these genes could in turn be associated with cannabis dependence." (PMID 22745721, 2012). "A significant statistical impact of cannabis dependence or absence and DRD2 genotype rs1799732 was demonstrated for flux as a feature and score of the NEO-FFI agreeableness scale." (PMID 36078646, 2022). "While we replicated previous findings showing a role of DRD2 in negative reward learning, cannabis-dependence vulnerability did not appear to be driven by this association." (PMID 22745721, 2012). "As such, we focused a priori on whether individual genetic differences of the DRD2 and PENK genes associate with cannabis dependence and explored the possible mediation or moderation of intermediate endophenotypes in the genetic associations." (PMID 22745721, 2012). "In evaluating genetic differences between cannabis and control subjects in regard to the DRD2 and PENK genes, it was observed that several DRD2 and PENK SNPs studied modulated cannabis-dependence outcomes." (PMID 22745721, 2012). "Overall, our results further support the role of DRD2 in negative reward learning, and suggest a central role for Neuroticism as an endophenotype linking PENK polymorphism to cannabis-dependence vulnerability synergistically amplifying the apparent genetic risk." (PMID 22745721, 2012).
cocaine abuse (7 papers, 2013 to 2024). Disorders related or resulting from use of cocaine. "For instance, two intronic SNPs in the type 2 dopamine receptor gene (DRD2) have been found sufficient to affect alternative splicing and therefore susceptibility to cocaine abuse." (PMID 24324616, 2013). "We found that FXYD2 and DRD2 mRNA expression was inversely correlated in both mouse purified iMSNs and human postmortem caudate (whole-tissue RNAseq) of individuals with severe cocaine abuse history and control subjects." (PMID 37881572, 2023).
endometrial cancer (7 papers, 2019 to 2024). Primary or metastatic malignant neoplasm involving the endometrium (mucous membrane that lines the endometrial cavity). "Increasing DRD2 expression in endometrial cancer was significantly associated with grade, serous histology and stage, as well as worse progression free survival and overall survival." (PMID 33557912, 2021). "DRD2 mRNA expression from the Cancer Genome Atlas (TCGA) database was compared between the four molecular subtypes of endometrial cancer." (PMID 33557912, 2021). "ONC201 has anti-tumorigenic effects in endometrial cancer cells and a transgenic mouse model of endometrial cancer, and DRD2 expression was documented in both human serous and endometrioid endometrial cancer." (PMID 33557912, 2021). "We then analyzed TCGA RNA-seq data generated from endometrial cancer to investigate the differential expression of DRD2 in different subtypes." (PMID 32867127, 2020). "The imipridone ONC206 is an orally bioavailable dopamine receptor D2 antagonist and mitochondrial protease ClpP agonist that has anti-tumorigenic effects in endometrial cancer via induction of apoptosis, activation of the integrated stress response and modulation of PI3K/AKT signaling." (PMID 37069726, 2023). "Indeed, the targeted DRD2 gene, a dopamine receptor, shows increased expression in many tumors and its inhibition demonstrated effectiveness in suppressing the proliferation of endometrial cancer cells, as well as reducing tumor growth and metastatic potential." (PMID 39273521, 2024). "It has been observed that as endometrial cancer progresses, expression of CXCL12, GNAL, OPRK1, DRD2, and DRD3 increases while DRD5 and COMT levels are gradually reduced." (PMID 34768458, 2021). "In contrast, DRD5 expression was decreased, while DRD2 and DRD3 levels were significantly increased in endometrial cancer." (PMID 34768458, 2021). "Expression of CXCL12, OPRK1, DRD5, COMT, DRD2, and DRD3 proteins was assessed in the serum of endometrial cancer patients and control group using ELISA." (PMID 34768458, 2021). "These preclinical studies provide a fundamental rationale for investigating DRD2 antagonism with ONC201 in EC, with phase 2 clinical trials in type 1 and 2 endometrial cancer ongoing and which will hopefully mature in the upcoming year." (PMID 33557912, 2021). "Microarray analysis showed that DRD2 was overexpressed regardless of endometrial cancer grade, while COMT and DRD5 showed a significant decrease in expression." (PMID 34768458, 2021).
Glucose intolerance (7 papers, 2016 to 2025). Glucose intolerance (GI) can be defined as dysglycemia that comprises both prediabetes and diabetes. "Furthermore, exposure to a HFD for 8 weeks also induced glucose intolerance in Drd2 loxP/loxP mice." (PMID 35757410, 2022).
memory impairment (7 papers, 2021 to 2025). "Neural circuit tracing, fiber photometry, and opto-chemogenetic approaches were used to assess Drd2 in the gating of the mPFC-basolateral amygdala (BLA) circuit-mediated memory impairment induced by CSD." (PMID 40963920, 2025). "These include both serious ADRs (heart failure for ADRA2B, DRD1, and DRD2 activation) and lower severity effects (sleep or memory impairments for several targets)." (PMID 37468498, 2023). "As predicted by network pharmacology methods, CASP3, BDNF, MAPK3, CREB1, and DRD2 were the hub genes in krill oil to alleviate METH-induced memory impairment." (PMID 34776973, 2021). "Next, we investigated whether Drd2 is essential for CSD-induced learning and memory impairment through micro-infusion of a Drd2 antagonist, Trifluoperazine 2HCl (TF), into the mPFC 10 min before the Y-maze test." (PMID 40963920, 2025).
Anorexia (6 papers, 2014 to 2025). Lack of desire to eat (loss of appetite). "In Ghsr+/+ mice, food intake was markedly inhibited by cabergoline compared to vehicle treated animals, but Ghsr−/−mice were refractory to cabergoline-induced anorexia; hence, the anorexigenic activity of DRD2 is dependent upon GHSR1a." (PMID 25183960, 2014). "Further, Ghsr+/+ mice treated with a neutral GHSR1a antagonist (the triazole, JMV2959) are resistant to DRD2 agonist-induced anorexia." (PMID 25183960, 2014).
conduct disorder (6 papers, 2007 to 2024). A disorder diagnosed in childhood or adolescence age group characterized by aggressive behavior, deceitfulness, destruction of property or violation of rules that is persistent and repetitive, and within a one year period. "This study examined whether adolescent conduct disorder and adult antisocial behavior were related to the dopamine D2 receptor polymorphism (DRD2) and the dopamine D4 receptor polymorphism (DRD4)." (PMID 17587443, 2007). "More importantly, the human ortholog of this gene, DRD2 (dopamine receptor D2, DIOPT v8.0 score = 9), is implicated in several diseases including ADHD, conduct disorder, and movement disease." (PMID 37957291, 2024). "The results suggest that a gene × gene interaction between DRD2 and DRD4 is associated with the development of conduct disorder and adult antisocial behavior in males." (PMID 17587443, 2007). "In this study, we test whether DRD2 and DRD4 are associated with multiple measures of conduct disorder and with a measure of antisocial behavior." (PMID 17587443, 2007). "However, DRD2 interacted with DRD4 to predict variation in adolescent conduct disorder and in adult antisocial behavior." (PMID 17587443, 2007). "The left hand side of the table reveals that DRD2 has a marginally significant effect on conduct disorder (b = .141, p = .059), whereas DRD4 does not exert an independent effect on the wave 1 conduct disorder scale (b = .036, p = .656)." (PMID 17587443, 2007). "Multivariate regression analysis revealed that neither DRD2 nor DRD4 had significant independent effects on conduct disorder or antisocial behavior." (PMID 17587443, 2007). "Over the last decade, several candidate genes (i.e., MAOA, DRD4, DRD2, DAT1, 5-HTTLPR, and COMT) have been extensively studied as potential moderators of the detrimental effects of postnatal family adversity on child externalizing behaviors, such as aggression and conduct disorder." (PMID 26537239, 2015).
endometriosis (6 papers, 2020 to 2026). The growth of functional endometrial tissue in anatomic sites outside the uterine body. "DRD2 is also expressed in human eutopic and ectopic endometrium, with DRD2 polymorphisms identified as endometriosis candidate genes in women with peritoneal moderate/severe endometriosis." (PMID 37371546, 2023). "Similarly, dopaminergic signaling may also be crucial in the prevention or hindrance of adenomyosis, especially in view of the evidence that dopamine D2 receptor (DRD2) signaling is seemingly depressed in the development of endometriosis." (PMID 33602248, 2021). "We next examined immunoreactivity against ADRB2, DRD2, α-SMA, CD31-stained MVD, E-cadherin, along with the extent of fibrosis via Masson trichrome staining, in all lesions from mouse with induced endometriosis." (PMID 32532293, 2020). "While a drug like cabergoline may have potential as an endometriosis therapeutic, it targets more than just DRD2, making a more selective DRD2 inhibitor such as ONC201 more suitable for targeting DRD2 in endometriosis." (PMID 37371546, 2023). "In endometriosis, increased release of catecholamines due to the activation of the HPA/SAM axes resulting from stress can also induce the ADRB2/CREB/PKA signaling pathway but suppress the expression of DRD2, accelerating the progression of endometriosis." (PMID 33446725, 2021).
injury (6 papers, 2015 to 2026). Damage inflicted on the body as the direct or indirect result of an external force, with or without disruption of structural continuity. "COMT and DRD2 are involved in dopaminergic transmission, which is altered after head trauma and contributes to changes in cognition and behavior." (PMID 41301762, 2025). "We then examined the effect of mechanical stretch on the pulmonary levels of DRD1, DRD2, TH and DDC in a murine model of mechanical ventilation-induced lung injury." (PMID 33456556, 2021).
leukemia (6 papers, 2019 to 2022). A malignant (clonal) hematologic disorder, involving hematopoietic stem cells and characterized by the presence of primitive or atypical myeloid or lymphoid cells in the bone marrow and the blood. "DRD2 Inhibition through genetic or pharmacological approaches has been shown to cause apoptosis and induce cell cycle arrest in leukemia, lung, colon, breast, endometrial, cervical, ovarian, pancreatic and brain cancer cells." (PMID 35372029, 2022). "DRD2− cells also possessed leukemia initiation capacity; however, the absence of DRD2 signal by flow cytometry does not rule out the presence of intracellular DRD2 expression." (PMID 33665638, 2021). "For example, treatment with the DRD2 antagonist, thioridazine, revealed in vivo anti-CSC activity by reducing leukemic stem cell function in forming leukemia." (PMID 35461314, 2022). "We reveal that in DRD2+ AML patients, DRD signaling in leukemic progenitors provides leukemia-exclusive networks of sensitivity that spare healthy hematopoiesis." (PMID 33665638, 2021).
opioid dependence (6 papers, 2014 to 2024). "Findings from candidate gene studies suggest that individuals with alcohol and opioid dependence are more likely to have shared genetic variants and be homozygous (A1/A1) or heterozygous (A1/A2) for the dopamine receptor coding gene (DRD2)." (PMID 35395044, 2022). "DRD2/ANKK1 TaqIA polymorphism is associated with opioid dependence risk, when individual is diagnosed with phlegm syndrome." (PMID 26138154, 2015). "The rs1799978 SNP of DRD2 has only been examined in association with opioid dependence or methadone dose in two single-SNP and haplotype analyses." (PMID 26437921, 2015). "Our review shows that the homozygous Ins/Ins wild-type DRD2-141C Ins/Del polymorphism rs 1799732 may be a risk factor for opioid dependence." (PMID 39595582, 2024). "In recent years, The meta-analysis suggested that DRD2/ANKK1 TaqIA polymorphism might be associated with opioid dependence risk." (PMID 26138154, 2015).
bruxism (5 papers, 2020 to 2025). Excessive clenching of the jaw and grinding of the teeth. "Variants in the DRD2 gene have been associated with bruxism and also with sleep disorders, including restless legs syndrome and periodic limb movement disorder, both of which potentially share some neurophysiological similarities with OSA." (PMID 39685550, 2024). "Motivated by the evidence of a genetic component to bruxism, association studies with common genetic variants have been conducted, suggesting an association exists between genes and bruxism (dopamine receptor D genes DRD2, DRD3, DRD5, and the 5-hydroxytryptamine receptor 2A gene, HTR2A)." (PMID 32471213, 2020). "Notably, the G allele of the DRD2 rs1800497 SNP has been associated with a significant reduction in the risk of awake-sleep bruxism, a phenomenon hypothesized to act as a protective mechanism against hypoxia in OSA." (PMID 40832754, 2025). "Polymorphisms in DRD2 related to bruxism phenotypes in children is a genetic variation in the dopamine receptor D2 (DRD2) that may alter dopamine signaling and modify the rewarding effects of food and videogame playing and could explain the relationship between SB, sugar, and screen overuse." (PMID 37252006, 2023). "Variations in genes like 5HTR2A, DRD2, DRD3, ANKK1, COMT, MMP9, ACTN3, and ANKK1 are linked with the susceptibility to Bruxism." (PMID 40291793, 2025). "Variants in the DRD1, DRD2, and DRD3 genes, which encode the dopamine D1, D2, and D3 receptors, have been implicated in bruxism." (PMID 39685550, 2024). "SNP in the DRD2 gene was associated with bruxism and its circadian phenotype, whereas SNPs in ANKK1 and COMT were found to be associated with circadian phenotypes of bruxism." (PMID 37252006, 2023).
Cerebral ischemia (5 papers, 2013 to 2025). Restriction of arterial blood supply to the brain associated with insufficient oxygenation to support the metabolic requirements of the tissue. "In summary, our study demonstrates that Sino possesses potent therapeutic effects in cerebral ischemia and suppresses neuroinflammatory injury via targeting astrocytic DRD2 and the CRYAB/STAT3 pathway." (PMID 27724964, 2016). "Taken together, our findings suggest that Sino exerts potent therapeutic effects in cerebral ischemia by targeting astrocytic DRD2 and suppressing neuroinflammatory injury via the CRYAB/STAT3 pathway." (PMID 27724964, 2016). "Our findings provided evidence that astrocytic DRD2 mainly contributed to the anti-inflammatory effect of Sino after cerebral ischemia." (PMID 27724964, 2016).
Chorea (5 papers, 2013 to 2025). Chorea (Greek for 'dance') refers to widespread arrhythmic involuntary movements of a forcible, jerky and restless fashion. "We describe a 4‐generation Dutch pedigree with a unique dominantly inherited clinical phenotype of a combined progressive chorea and cervical dystonia carrying a novel heterozygous dopamine D2 receptor (DRD2) variant." (PMID 33200438, 2021). "Future studies are needed to confirm whether mutations in DRD2 are a more common cause of chorea." (PMID 33200438, 2021).
Huntington disease (5 papers, 2009 to 2024). Huntington disease (HD) is a rare neurodegenerative disorder of the central nervous system characterized by unwanted choreatic movements, behavioral and psychiatric disturbances and dementia. "The progression of Huntington’s Disease (HD) predominantly impacts spiny projection neurons (SPNs) in the striatum, with Drd2-expressing iSPNs being particularly susceptible compared to Drd1-expressing dSPNs." (PMID 38918688, 2024). "A transgenic mouse was generated as an animal model of Huntington’s disease (HD) in which Drd1a+ cells were slowly but progressively ablated in the postnatal striatum, yet Drd2 single-positive cells were preserved." (PMID 34067192, 2021). "Furthermore, we found that some DORCs, such as CNR1, HOMER1, ADORA2A, and DRD2, have been reported to be downregulated in patients with Huntington's disease in the striatum." (PMID 38091510, 2022).
insomnia (5 papers, 2019 to 2025). A sleep disorder characterized by difficulty in falling asleep and/or remaining asleep. "Tetradecanoic acid (Z-score = − 1.00) potentially affects several important proteins-associated with insomnia, including ADRB2, DRD2, and SCN2A." (PMID 37573423, 2023). "The results from the PPI analysis show that the targets of VVO for the treatment of insomnia mainly involve MAOB, DRD2, MAOA, IL1B, PTGS2, HTR2A, SLC6A4, and ESR1." (PMID 40004189, 2025).
ischemic stroke (5 papers, 2016 to 2025). A stroke disorder caused by obstruction of blood flow to the brain, due to thrombotic (local blood clot formation) or embolic (due to a blood clot or other material traveling from another site) event. "Our study demonstrates that Sino activates astrocytic DRD2 and thereby suppresses neuroinflammation via the CRYAB/STAT3 pathway, which sheds some light on a promising therapeutic strategy for ischemic stroke." (PMID 27724964, 2016). "Our results indicated that Sino suppresses the neuroinflammation via targeting the astrocytic DRD2/CRYAB/STAT3 pathway in cerebral ischemic model in vivo and in vitro, which sheds some light on a promising therapeutic strategy for ischemic stroke." (PMID 27724964, 2016).